NDUFS1 (NADH:ubiquinone oxidoreductase core subunit S1)
Diseases named in the same sentence as NDUFS1 in open-access papers (continued):
Sharing a sentence is not in itself a finding about the gene and the disease.
cancer (22 papers, 2016 to 2025). A tumor composed of atypical neoplastic, often pleomorphic cells that invade other tissues. "Amplifications in genes such as SLC3A2, OXSM, and GYS1 were linked to increased expression in cancer tissues, whereas genes such as NDUFS1 and NCKAP1 showed reduced expression, underscoring the diverse impact of DRG expression on BLCA pathology." (PMID 38507521, 2024). "The nine genes identified in our signature (Dhx9, Dusp12, Fhl1, Ifitm1, Ndufs1, Pja2, Slc1a3, Soga1, and Spon2) have each been investigated for their role in cancer." (PMID 38193115, 2024). "The disulfidptosis genes: NCKAP1, LRPPRC, SLC7A11, OXSM, SLC3A2, NDUFS1, and GYS1 occurred somatic mutations in pan-cancer, with 1 % SNV frequency." (PMID 39605832, 2024). "To extend our analysis of NDUFS1 mRNA level in KIRC to the universal expression profiles in other cancer types, we further investigated the Oncomine and TIMER databases." (PMID 37469574, 2023). "Notably, NDUFA11, OXSM, LRPPRC, NCKAP1, RPN1, SLC3A2, and SLC7A11 were upregulated in cancer tissues, while NDUFS1 showed the opposite trend." (PMID 38213838, 2023). "Accumulating evidence suggests that alteration of NDUFS1 may critically contribute to cancer progression." (PMID 37644092, 2023). "find that cancer cells require NDUFS1 and other OXPHOS genes for survival in acidic environments." (PMID 35263578, 2022). "Meanwhile, NDUFS1 (an important component of the complex I) overexpression could enhance the complex I activity, reverse glycolysis and resensitize cancer cells to radiation in vivo and in vitro." (PMID 34489398, 2021). "Here we reveal that NDUFS1 overexpression could enhance the complex I activity, reverse glycolysis and resensitize cancer cells to radiation in vivo and in vitro." (PMID 34489398, 2021). "Therefore, underexpression of NDUFS1 suggests that mitochondrial function is compromised in cancer patients, with a direct effect on the fertilizing capacity of spermatozoa." (PMID 32942548, 2020). "Accordingly, loss of NDUFS1 may disrupt the native NADH homeostasis function of complex I and lead to cancer progression." (PMID 27516145, 2016). "We speculated that although the increase in ROS by doxorubicin or cisplatin would facilitate cell death in the majority of A549 cancer cells, it could potentially increase Ndufs1 oxidation, and subsequently the formation of ETC supercomplexes in a small subset of cells, facilitating chemoresistance." (PMID 40752580, 2025). "Moreover, altered expression of proteins (NDUFS1, SOD1, SERPINA5, and UQCRC2) involved in sperm fertility potential and motility suggests that the fertility of cancer patients may be at risk due to the aberrant expression of critical sperm proteins." (PMID 32942548, 2020). "For instance, in most cancer types, the expression of SLC7A11, OXSM, and NDUFS1 was negatively correlated with methylation." (PMID 38397869, 2024). "We found that the expression of GYS1 and SLC7A11 were upregulated, while those of NCKAP1, NDUFS1, NUBPL, OXSM, RPN1, and SLC3A2 were downregulated in ccRCC tissues compared with those in the para-carcinoma tissues." (PMID 38271056, 2024). "Targeting genes such as NDUFS1, NFU1, or IBA57 is therefore a potential route for selectively killing cancer cells in acidic microenvironments." (PMID 35263578, 2022). "Western blot validation of NDUFS1 and UQCRC2 protein expression in cancer patients were in accordance with the proteomic results." (PMID 32942548, 2020). "The analysis revealed the underexpression of NDUFS1 and UQCRC2 in all the cancer types compared to the fertile men." (PMID 32942548, 2020). "Although the expression profiles and prognosis values of NDUFS genes in KIRC have been reported recently, the relationship between NDUFS1 and immune cell infiltration in cancer have not been explored." (PMID 37469574, 2023).
cancer (continued). "NDUFS1, the gene with the most present variant (NDUFS1.1868T>G) in different samples in our cohort and not yet reported, and NDUFS2 have already been linked to cancer, mitochondrial diseases and being associated with oncogenes." (PMID 39684297, 2024).
infection (4 papers, 2022 to 2025). The state of being infected such as from the introduction of a foreign agent such as serum, vaccine, antigenic substance or organism. "Here, we provide evidences to show that RRSV manipulates the NDUFS1-mediated mitochondrial apoptosis to promote its infection in N. lugens." (PMID 40828869, 2025).
cardiovascular diseases (2 papers, 2022 to 2024). "This evidence suggests that Ndufs1 may have similar mechanisms of action in various cardiovascular diseases and is a valuable therapeutic target." (PMID 35817848, 2022).
mitochondrial disease (2 papers, 2021 to 2024). "Many mitochondrial disease-related altered proteins also formed part of the energy network (DLD, NDUFA4, NDUFB5, NDUFB6, NDUFB9, NDUFS1, NDUFA12 and UQCRB) and belong to respiratory electron transport with the exception of DLD, which belongs to the TCA cycle." (PMID 34576238, 2021).
head and neck tumors (1 paper, 2025). "In this study, we found that MRPL21 interacted with NDUFS1 and promoted mitochondrial OXPHOS function and NAD + level enhancing energy production and proliferation in head and neck tumors." (PMID 40713706, 2025).
NDUFS1 also shares sentences with these, for which no sentence is quoted: leukemia (3 papers); leukodystrophy (3); lymphoma (3); Alzheimer disease (2); clear cell renal adenocarcinoma (2); endometrial cancer (2); maturity-onset diabetes (2); Myocardial Hypertrophy (2); prostate carcinoma (2); adenocarcinoma (1); basal ganglia disorder (1); Brain atrophy (1); brain diseases (1); brain tumor (1); cervical cancer (1); cholangiocarcinoma (1); diabetic kidney disease (1); Down syndrome (1); genetic diseases (1); head and neck squamous cell carcinoma (1); hepatocellular carcinoma (1); Hodgkin’s disease (1); Huntington disease (1); hypertrophic cardiomyopathy (1); immune diseases (1); Intellectual disability (1); iron deficiency (1); lactic acidosis (1); Left ventricular dilatation (1); liver cancer (1).
A further 18 diseases each share a sentence with NDUFS1 in 1 paper.